RNU6-50P (RNA, U6 small nuclear 50, pseudogene)
Synonyms: U6; LOC124900488; formerly RNU6P1; RNU6-50
Gene: Small nuclear RNA gene on chromosome X (46,517,766 to 46,517,868, forward strand). Ensembl gene ENSG00000199226.
Homologues: Orthologues: chimpanzee U6 (100% identical), macaque U6 (95% identical), guinea pig U6 (84% identical), rat LOC120094975 (78% identical), pig U6 (72% identical), mouse Gm22236 (66% identical), dog U6 (63% identical), rat LOC120093928 (62% identical). Paralogues in human: RNU6-1122P (82% identical), RNU6-333P (82% identical), RNU6-820P (82% identical), RNU6-1011P (81% identical), RNU6-1029P (81% identical), RNU6-1060P (81% identical), RNU6-1078P (81% identical), RNU6-12P (81% identical), RNU6-13P (81% identical), RNU6-16P (81% identical), RNU6-25P (81% identical), RNU6-29P (81% identical), and 1288 more.